LINC00423 (long independently transcribed non-coding RNA 423)
Gene: Long non-coding RNA gene on chromosome 13 (32,877,431 to 32,911,650, reverse strand). Ensembl gene ENSG00000226968.
Diseases named in the same sentence as LINC00423 in open-access papers:
LINC00423 is named in the same sentence as 1 disease in open-access papers, as found by Europe PMC text mining. Sharing a sentence is not in itself a finding about the gene and the disease. The quoted sentences say what the papers report.
tumor (1 paper, 2019). "Summing up, our findings demonstrated that linc00423 acted as the tumor suppressor in RLS cells through regulating the protein level of NFATC3 at a post-transcriptional level and negatively regulated the MAPK signaling pathway at a transcriptional level." (PMID 31160581, 2019). "Taken together, both linc00423 and NFATC3 were as tumor suppressors in RLS, they make a meaningful contribution to cell proliferation through regulated the MAPK signaling pathway." (PMID 31160581, 2019). "Therefore, we also analyze that the correlation of linc00423 and DDIT3 results showed that linc00423 had a positive correlation with DDIT3, suggesting that linc00423 may be a tumor-suppressor gene in RLS (P < 0.0001)." (PMID 31160581, 2019).